INTS6 (integrator complex subunit 6)
Description:
Component of the integrator complex, a multiprotein complex that terminates RNA polymerase II (Pol II) transcription in the promoter-proximal region of genes. The integrator complex provides a quality checkpoint during transcription elongation by driving premature transcription termination of transcripts that are unfavorably configured for transcriptional elongation: the complex terminates transcription by (1) catalyzing dephosphorylation of the C-terminal domain (CTD) of Pol II subunit POLR2A and SUPT5H/SPT5, (2) degrading the exiting nascent RNA transcript via endonuclease activity and (3) promoting the release of Pol II from bound DNA. The integrator complex is also involved in terminating the synthesis of non-coding Pol II transcripts, such as enhancer RNAs (eRNAs), small nuclear RNAs (snRNAs), telomerase RNAs and long non-coding RNAs (lncRNAs). Within the integrator complex, INTS6 acts as a molecular adapter that promotes assembly of protein phosphatase 2A (PP2A) subunits to the integrator core complex, promoting recruitment of PP2A to transcription pause-release checkpoint. Mediates recruitment of cytoplasmic dynein to the nuclear envelope, probably as component of the integrator complex. May have a tumor suppressor role; an ectopic expression suppressing tumor cell growth.
Synonyms: Int6; DICE1; DDX26; DDX26A; HDB; Notchl2; DBI-1
Tractability: PROTAC: ubiquitination databases record sites on it; its protein half-life has been measured.
Gene: Protein-coding gene on chromosome 13 (51,354,077 to 51,454,264, reverse strand). Ensembl gene ENSG00000102786.
Subcellular location: Nucleus; Chromosome
Subcellular location (Human Protein Atlas): Nucleoplasm; Actin filaments
Pathways (Reactome):
Gene expression (Transcription): RNA polymerase II transcribes snRNA genes
Gene Ontology:
Molecular function: protein binding; protein-macromolecule adaptor activity; transmembrane signaling receptor activity
Biological process: protein localization to chromatin; regulation of transcription elongation by RNA polymerase II; RNA polymerase II transcription initiation surveillance; snRNA processing; snRNA 3'-end processing
Cellular component: chromatin; chromosome; INTAC complex; integrator complex; nucleoplasm; nucleus
Genetic constraint (gnomAD): Loss-of-function variants: 10 observed, 73.8 expected, observed/expected ratio (o/e) 0.14, 90% interval 0.083 to 0.23. The upper end of that interval is the gene's LOEUF score, 0.23, which puts it in group 1 of 6, group 1 being the genes least tolerant of losing a copy. Missense variants: 501 observed, 880.65 expected, observed/expected ratio (o/e) 0.57, 90% interval 0.53 to 0.61. Synonymous variants: 283 observed, 304.08 expected, observed/expected ratio (o/e) 0.93, 90% interval 0.84 to 1.03.
Homologues: Orthologues: chimpanzee INTS6 (99% identical), macaque INTS6 (99% identical), pig INTS6 (99% identical), dog INTS6 (98% identical), mouse Ints6 (96% identical), rat Ints6 (96% identical), rabbit INTS6 (92% identical), guinea pig INTS6 (80% identical), tropical clawed frog ints6 (77% identical), zebrafish ints6 (67% identical), Drosophila melanogaster IntS6 (40% identical), Caenorhabditis elegans ints-6 (26% identical). Paralogues in human: INTS6L (69% identical), SAGE1 (14% identical), CT45A10 (6% identical), CT45A2 (6% identical), CT45A5 (6% identical), CT45A6 (6% identical), CT45A7 (6% identical), CT45A8 (6% identical), CT45A9 (6% identical), CT45A3 (5% identical), CT45A1 (5% identical).
Diseases named in the same sentence as INTS6 in open-access papers:
INTS6 is named in the same sentence as 37 diseases in open-access papers, as found by Europe PMC text mining. Sharing a sentence is not in itself a finding about the gene and the disease. The quoted sentences say what the papers report.
prostate carcinoma (9 papers, 2008 to 2025). A carcinoma that arises from epithelial cells of the prostate gland. "Moreover, another study of INTS6 in prostate cancer shows that lower expression of INTS6 can cause hypermethylation of the promoter region CpG." (PMID 28899352, 2017). "Furthermore, the low expression level of INTS6 in prostate cancer has been found to be caused, in part, by promoter region CpG hypermethylation." (PMID 25686840, 2015). "INTS6 exhibits significantly down-regulated expression levels in non-small cell lung cancer and prostate cancer compared to normal tissues." (PMID 38926181, 2024). "Some studies have identified the promoter of the tumour suppressor gene INTS6, which is down-regulated in prostate cancer, and have revealed that the INTS6 promoter is hypermethylated in prostate cancer cell lines." (PMID 28899352, 2017). "In mechanistic studies, INTS6 tends to induce the Gap 1 (G1) arrest, thus explaining its tumour suppressor role in prostate cancer." (PMID 28899352, 2017). "Mechanistically, INTS6 appears to induce Gap 1 (G1) arrest, explaining, in part its tumor suppressive roles in prostate cancer." (PMID 25686840, 2015). "Several studies have suggested that INTS6 plays tumor suppressive roles in several human cancers, such as non-small cell lung carcinoma, esophageal squamous cell carcinoma and prostate carcinoma." (PMID 25686840, 2015). "Markedly decreased INTS6/DICE1 mRNA levels were detected in prostate cancer cell lines LNCaP, DU145 and PC3 as well as CPTX1532 as compared to a cell line derived from normal prostate tissue, NPTX1532." (PMID 19906297, 2009). "Given that INTS6 downregulation has also been observed in several other malignancies, including breast, lung, and prostate cancers, the therapeutic strategy proposed in this study may have broader applicability beyond HCC." (PMID 41020855, 2025). "Furthermore, promoter CpG hypermethylation and the downregulation of INTS6/DICE1 expression was also observed in prostate cancer cells." (PMID 28468258, 2017). "Together, these results suggest INTS6/DICE1 as a putative tumor suppressor gene in prostate cancer." (PMID 19906297, 2009). "In prostate cancer with down-regulated INTS6/DICE1 expression, its exogenous expression may result in reassembly of DICE1 containing multi-protein complexes thus affecting distinct signaling pathways." (PMID 19906297, 2009). "INTS6/DICE1 missense mutations have been previously detected in lung and prostate cancer cell lines NCI-H2126 and LNCaP respectively, and reduced INTS6/DICE1 expression appears to be associated with CpG promoter hypermethylation in lung and prostate cancer cells." (PMID 19906297, 2009). "Regarding prostatic tumorigenesis, INTS6/DICE1 expression is down-regulated in multiple prostate cancer cell lines as compared to normal prostate cells, and its exogenous re-expression in cancer cells leads to inhibition of their capacity to form colonies in vitro." (PMID 19906297, 2009). "In this study, we examined the growth inhibitory effects of INTS6/DICE1 on prostate cancer cells." (PMID 19906297, 2009). "The gene encoding integrator complex subunit 6 (INTS6), previously known as deleted in cancer cells 1 (DICE1, OMIM 604331) was found to be frequently affected by allelic deletion and promoter hypermethylation in prostate cancer specimens and cell lines." (PMID 19906297, 2009). "INTS6 (DICE1), a DEAD box protein that exhibits tumor suppressor activity, is hypermethylated and downregulated in prostate cancer." (PMID 18828910, 2008). "Deleted In Cancer 1 (INTS6/DICE1) gene (OMIM 604331) was identified to colocalize with the microsatellite marker D13S284 in 13q14.3, a region frequently affected by allelic deletion in many solid tumors including prostate cancer." (PMID 19906297, 2009).
hepatocellular carcinoma (6 papers, 2015 to 2025). A malignant tumor that arises from hepatocytes. "Functional studies were conducted using a hepatoma cell line to determine the effects of INTS6 modulation on tumor behavior." (PMID 41020855, 2025). "In this study, we wanted to determine the expression level of INTS6 in hepatocellular carcinoma (HCC) and evaluate its clinical characteristics and mechanisms in HCC patients (Lui and Lu, European Journal of Cancer, 51:S94, 2015)." (PMID 28899352, 2017). "Both INTS6 and pseudogene INTS6P1 play roles in repressing hepatocellular cancer by competing for onco‐miR‐17‐5p binding, which facilitates hepatocellular cancer initiation and progression." (PMID 27561207, 2017). "The human INTS6 (originally named deleted in cancer 1, DICE1) was first identified as a tumor suppressor in lung and squamous cell carcinomas and was recently shown to also act as a tumor suppressor in hepatocellular carcinomas." (PMID 31311534, 2019).
breast cancer (2 papers, 2010 to 2011). A primary or metastatic malignant neoplasm involving the breast. "We find that amplification of the MYC locus and the loss of the RB/INTS6 locus is evolutionarily conserved in mouse and human mammary tumor development, and that AURKA amplification is conserved in mouse and human BRCA2-mutated tumors." (PMID 20735817, 2010). "Similar to MYC gain, RB1/INTS6 loss could be evolutionarily conserved in mammary tumor development." (PMID 20735817, 2010).
colorectal tumor (2 papers, 1999 to 2024). "In this work, we classified a cohort of colorectal tumors by measuring the degree of snRNA processing and found that the lack of snRNA processing has a better prognostic value than the amount of INTS6 mRNA." (PMID 39001402, 2024). "Our results show a positive correlation between levels of unprocessed snRNAs and INTS6 mRNA in colorectal tumors." (PMID 39001402, 2024). "While INTS6 is highly downregulated in most of the tumors and therefore is suggested to play a role as a tumor suppressor, in other tumors, such as colorectal tumor, INTS6 is markedly upregulated, showing, in this case, an oncogenic activity." (PMID 39001402, 2024). "Therefore, we concluded that the multiple tumors represented in the selected cohort allowed us to study the effect of snRNA processing and INTS6 levels in different types of colorectal tumors." (PMID 39001402, 2024). "In conclusion, levels of unprocessed U2snRNAs (but not INTS6 mRNA levels) may be a good biomarker for diagnosis/prognosis of colorectal tumors." (PMID 39001402, 2024).
esophageal squamous cell carcinoma (2 papers, 2015 to 2017). Esophageal squamous cell carcinoma (ESCC) is a type of esophageal carcinoma (EC) that can affect any part of the esophagus, but is usually located in the upper or middle third. "Indeed, INTS6/DICE1 was earlier identified as a tumor suppressor gene in lung carcinomas where it was frequently downregulated, and in esophageal squamous cell carcinomas where mutations occurred, although at a low frequency." (PMID 28468258, 2017).
lung carcinoma (2 papers, 2017 to 2019). "Since the characterization of Ints6, named at that time as DICE1 (deleted in cancer 1), as a tumor suppressor in lung carcinomas, mutations in the different Integrator complex subunits have been reported as involved in multiple kind of tumors." (PMID 30807579, 2019).
Anxiety (1 paper, 2025). Intense feelings of nervousness, tension, or panic often arise in response to interpersonal stresses. "In the elevated plus maze, Ints6 cHET mice had significantly increased movement time and distance within the open arms of the maze, alongside enhanced movement in the closed arms, suggesting that Ints6 deficiency may contribute to hyperactivity rather than traditional anxiety-like behavior." (PMID 40966122, 2025).
autism (1 paper, 2025). Persistent deficits in social interaction and communication and interaction as well as a markedly restricted repertoire of activity and interest as well as repetitive patterns of behavior. "INTS6 monoallelic variants are associated with core features of developmental delay and autism, with a potential male predominance." (PMID 40966122, 2025).
Cirrhosis (1 paper, 2017). A chronic disorder of the liver in which liver tissue becomes scarred and is partially replaced by regenerative nodules and fibrotic tissue resulting in loss of liver function. "However, neither immunohistochemistry nor qRT-PCR analyses of INTS6 expression had statistically significant associations with age, gender, HBsAg positivity, tumour size, or cirrhosis." (PMID 28899352, 2017). "Therefore, we propose that the expression level of INTS6 was largely due to the tumour itself rather than cirrhosis and HBsAg-positivity." (PMID 28899352, 2017).
cognitive deficits (1 paper, 2025). "Mice with Ints6 haploinsufficiency exhibited substantial social and cognitive deficits, along with impaired synaptic development." (PMID 40966122, 2025). "Ints6 haploinsufficiency leads to social and cognitive impairments in mice." (PMID 40966122, 2025).
cognitive delay (1 paper, 2025). "Variants in INTS8 result in severe cognitive delay, speech absence, and motor impairment, whereas monoallelic variants in INTS6 lead to milder phenotypes, including speech–language problems, motor delays, and intellectual disability." (PMID 40966122, 2025).
colorectal cancer (1 paper, 2024). A primary or metastatic malignant neoplasm that affects the colon or rectum. "To evaluate the value of snRNA processing and INTS6 mRNA levels as possible biomarkers for the diagnosis and prognosis of colorectal cancer, we performed a Spearman correlation analysis with the rest of the clinicopathological variables of the tumors." (PMID 39001402, 2024). "Our results strengthen the hypothesis that low Integrator-complex activity, but not necessarily low INTS6 expression, is associated with a poor prognosis in colorectal-cancer patients." (PMID 39001402, 2024). "In contrast, in colorectal cancer INTS6 expression is significantly increased when compared with normal tissues." (PMID 39001402, 2024). "Alternatively, INTS6 might be involved in tumors affecting other tissues, but not in colorectal cancer." (PMID 39001402, 2024).
fetal growth restriction (1 paper, 2024). A fetus that does not grow beyond the 10th percentile of conventionally accepted weight for gestational age. "Placental mRNA expression was examined for the 8 genes enriched in isolated trophoblast side-population cells (CXLC8/IL8, ELL2, GATA6, HK2, HLA-DPB1, INTS6, SERPINE3, UPP1) in placentas obtained from participants with early onset preeclampsia (n = 78) or fetal growth restriction (n = 30)." (PMID 39028417, 2024).
Intellectual disability (1 paper, 2025). "Phenotypically, individuals with INTS6 variants exhibit overlapping features, including language and motor delays, ASD, intellectual disabilities, sleep disturbances, and ADHD." (PMID 40966122, 2025).
leukemia (1 paper, 2025). A malignant (clonal) hematologic disorder, involving hematopoietic stem cells and characterized by the presence of primitive or atypical myeloid or lymphoid cells in the bone marrow and the blood. "Notably, the loss of INTS6 disrupts the recruitment of PP2A to CDK9 in leukemia and unspecified solid tumors, resulting in sustained CDK9 activity and resistance to CDK9 inhibitors." (PMID 41020855, 2025).
nasopharyngeal carcinoma (1 paper, 2022). A carcinoma arising from the nasopharyngeal epithelium. "Additionally, the tumor-suppressor deleted in cancer cells 1 (DICE1), also known as integrator complex subunit 6 (INTS6), was also shown to be downregulated by miR-BART3, which resulted in increased proliferation and transformation in nasopharyngeal cancer cells." (PMID 35889167, 2022).
parathyroid tumors (1 paper, 2009). "INTS6/DICE1 is also subject to regulation by the tumor suppressor CDC73 that is mutually inactivated in hereditary and sporadic parathyroid tumors." (PMID 19906297, 2009).
tumor (30 papers, 2008 to 2025). "Generally, INTS6 acts as a tumor suppressor, with their Loss of function potentially leading to tumorigenesis." (PMID 37537630, 2023). "Our data indicate that amplification of the MYC locus and loss of the RB/INTS6 locus occurs in all mouse and human tumor groups, and that AURKA amplification occurs in mouse and human BRCA2-mutated tumors." (PMID 20735817, 2010). "Principal common CNAs were the well known MYC-associated gain and RB1/INTS6-associated loss that occurred in all mouse and human tumor groups, and the AURKA-associated gain occurred in BRCA2-related tumors from both species." (PMID 20735817, 2010). "This means that loss of function of INTS6 is responsible for tumor transformation." (PMID 39001402, 2024). "In our study, we found that the correlation between a higher level of AFP (AFP ≥ 20 ng), lower pathology grade (poor) and tumour recurrence and a lower expression level of INTS6 may be associated with poor prognosis in HCC patients." (PMID 28899352, 2017). "Likewise, the chromosome 13 loss, associated with RB1 loss occurs in all human and mouse tumor groups, and all overlapping regions encompass the INTS6 gene." (PMID 20735817, 2010). "Other protective genes, including DYRK1A, DICER1, MYOD1 and INTS6, also contribute to tumor suppression through diverse mechanisms." (PMID 40561176, 2025). "The integrator complex subunit 6 (INTS6), a regulator of RNA polymerase II transcription, has emerged as a potential tumor suppressor that modulates Wnt/β-catenin signaling and epithelial–mesenchymal transition (EMT)." (PMID 41020855, 2025). "Given that INTS6 expression is frequently downregulated in tumor tissues, particular attention has been directed toward EMT regulation as a key mechanism underlying tumor progression and therapeutic resistance." (PMID 41020855, 2025). "INTS6P1 upregulated its cognate gene INTS6 through competitively binding to miR-17-5p, thereby functioning its tumor suppressive roles in HCC." (PMID 32185172, 2020). "qRT-PCR and Western blot analyses showed that the INTS6 mRNA and protein expression was significantly down-regulated in tumour tissues compared to the adjacent normal liver tissues (p<0.05)." (PMID 28899352, 2017). "The expression level of INTS6 was significantly associated with the serum alpha-fetoprotein level (AFP, p = 0.004), pathology grade (p = 0.005), and tumour recurrence (p = 0.040)." (PMID 28899352, 2017). "Stratified survival analysis explored the prognostic value of INTS6 according to poor pathology grade and tumour recurrence." (PMID 28899352, 2017). "Integrator complex subunit 6 (INTS6) was found to play a tumour suppressing role in certain types of solid tumours." (PMID 28899352, 2017). "Several studies have suggested that INTS6 plays an important role as a tumour suppressor in some human cancers." (PMID 28899352, 2017). "Univariate Cox regression analyses revealed that the expression of INTS6 (p = 0.001), pathology grade (p = 0.005), tumour size (p = 0.035), vascular invasion (p = 0.001) and recurrence (p = 0.002) correlated with overall survival." (PMID 28899352, 2017). "Taken together, these findings demonstrate INTS6P1 and INTS6 exert the tumor suppressive roles through competing for oncomiR-17-5p." (PMID 25686840, 2015). "Taken together, these findings suggest that INTS6P1 and INTS6 exert tumor suppressive effects by promoting HCC cell death and inhibiting cell mobility." (PMID 25686840, 2015). "The data presented herein warrants further studies in other human cancers, in particular its cognate gene, INTS6, is found to be a tumor suppressor." (PMID 25686840, 2015). "Previous studies suggested the tumor suppressive role for INTS6 in other cancer types, however, to date, there are no studies to report its role in HCC." (PMID 25686840, 2015). "Interestingly, re-expression of INTS6 cDNA in those tumor cell lines suppresses their high mitosis rate by regulating cell cycle progression." (PMID 39001402, 2024).